INS (insulin)
Diseases named in the same sentence as INS in open-access papers (continued):
Sharing a sentence is not in itself a finding about the gene and the disease.
coronary atherosclerosis (32 papers, 2009 to 2025). Atherosclerosis of the coronary vasculature. "In the same study, we demonstrated that insulin resistance of the EAT adipocyte in this category of patients was closely associated with the severity of coronary atherosclerosis." (PMID 36009601, 2022). "To this end, we used DM mice with coronary artery atherosclerosis, as well as mice that were insulin resistant." (PMID 40513100, 2025). "In patients with severe coronary artery atherosclerosis, systemic glucose/insulin metabolism disorders and decreased serum lipocalin were identified as significant independent factors contributing to the intensity of oxidative stress in EAT adipocytes." (PMID 39540983, 2025). "Our study is the first to show the effect of a DPP‐4i on coronary atherosclerosis as assessed by CCTA in T2DM patients receiving insulin therapy." (PMID 37528628, 2023). "In this study, we evaluated the benefit of a DPP‐4i on coronary atherosclerosis in T2DM patients receiving insulin therapy." (PMID 37528628, 2023). "Further prospective studies are required to confirm the role of oxidative stress of EAT adipocytes in mediating the relationships between impaired glucose/insulin metabolism, adipokines profile, and progression of coronary atherosclerosis." (PMID 36009601, 2022). "Excessive adiposity has a well-established role in coronary atherosclerosis by both secreting plenty of active cytokines and regulating insulin sensitivity." (PMID 35784958, 2022). "The percentages of patients treated with insulin were significantly correlated with the increasing extent of the coronary atherosclerosis." (PMID 26417150, 2015). "The present study showed that MVD, lower HDL, and insulin use were independent predictors of the development of new coronary artery atherosclerosis after PCI." (PMID 23807613, 2014). "However, only the group rendered insulin-dependent by the use of streptozotocin developed severe coronary artery atherosclerosis in short-term follow-up." (PMID 37759585, 2023). "A genetic study including 63,746 CAD patients and 130,681 healthy individuals reported that lipid metabolism and inflammation are key biological processes involved in the pathogenesis of coronary atherosclerosis, supporting the role of insulin resistance in the pathophysiology of CAD." (PMID 35778731, 2022). "However, in diabetic individuals also suffering from coronary atherosclerosis, GLUT4 levels in EAT were even lower, underlying in this way the local role of insulin-induced atherogenesis in CAD." (PMID 35784958, 2022). "Although CSF has been found to be related to microvascular diseases, vascular endothelial dysfunction, coronary atherosclerosis, oxidative stress, insulin resistance, adipocytokines, and abnormal blood composition, the exact mechanisms are still unknown." (PMID 32460702, 2020). "Thus, we concluded that the variables postprandial glucose, adiponectin, and postprandial insulin could be chosen as screening markers of EAT ROS increase in patients with coronary atherosclerosis." (PMID 36009601, 2022). "This study found a direct correlation between insulin resistance of EAT adipocytes and the severity of coronary atherosclerosis which is consistent with previous studies." (PMID 33440802, 2021). "Five additional pigs fed regular pig chow also developed increased insulin resistance but essentially no change in the other variables and little to no detectible coronary atherosclerosis." (PMID 26147990, 2015). "In summary, ADMA levels appear to reflect diffuse but not focal coronary atherosclerosis in non-diabetic men with stable CAD irrespective of the magnitude of impaired metabolic sensitivity to insulin." (PMID 24103320, 2013).
coronary atherosclerosis (continued). "Remote ischaemic conditioning (RIC) reduces ischaemia and reperfusion (I/R) injury in animal models but has failed to translate in large clinical trials, possibly because experiments often use healthy animals lacking coronary atherosclerosis,or co-morbidities such as insulin resistance." (PMID 40513100, 2025).
hyperprolactinemia (32 papers, 2013 to 2026). Abnormally high level of prolactin in the blood. "This is supported by the discovery of prolactin receptor expression on insulin-secreting cell lines, with chronic hyperprolactinemia also being linked to impaired insulin secretion." (PMID 38645431, 2024). "Increased plasma concentrations of insulin are associated with activation and upregulation of heat shock proteins and hyperprolactinemia." (PMID 37467251, 2023). "Hyperprolactinemia was associated with sexual dysfunction, female sex, higher insulin level, and younger age." (PMID 34421613, 2021). "Higher ASEX scores, higher insulin levels, female sex, and younger age were associated with hyperprolactinemia." (PMID 34421613, 2021). "Conversely, in some people, poor insulin secretion has been linked to chronic hyperprolactinemia." (PMID 39791749, 2025). "Therefore, hyperprolactinemia is associated with increased insulin secretion, and consequently, a decrease in glycemic values, as observed in our study in the women subgroup." (PMID 40650124, 2025). "Furthermore, chronic hyperprolactinaemia is associated with impaired insulin secretion and IR in many clinical studies." (PMID 39663784, 2024). "The absence of changes in glycemia in 12‐ and 18‐month‐old female rats may be related to the high concentration of PRL, as it has been reported that chronic moderate hyperprolactinemia is associated with increased release of insulin induced by a glucose load." (PMID 33075214, 2020). "The women with hyperprolactinemia (40.8%) had significantly higher BMI (p = 0.007), fasting glucose (p = 0.003), insulin levels (p < 0.001) and HOMA-IR (p < 0.001)." (PMID 40362476, 2025). "The comparative analysis indicated that patients with hyperprolactinemia had significantly higher body mass index, fasting plasma glucose, immunoreactive insulin, and HOMA-IR than normoprolactinemic patients." (PMID 40362476, 2025). "In particular, a reduction in glucose tolerance and a raise in fasting insulin (FI) have been found in patients with hyperprolactinemia, independently from Body Mass Index (BMI)." (PMID 36237192, 2022). "In patients with hyperprolactinemia, an increased response of insulin to glucose has been reported during the oral glucose tolerance test." (PMID 31191454, 2019). "In contrast to our findings, studies including pathological hyperprolactinemia caused by PRL-secreting tumors (prolactinomas) showed that, after treatment with dopamine agonists, reduced PRL concentrations led to increased insulin sensitivity." (PMID 23517652, 2013). "Hyperprolactinemia in patients with PCOS may additionally aggravate the decline in insulin sensitivity, attributable to prolactin lipogenic effects and influence on metabolic profile." (PMID 40362476, 2025). "However, the women with hyperprolactinemia had statistically significantly higher body mass index (BMI), fasting glucose and immunoreactive insulin (IRI) levels." (PMID 40362476, 2025). "In addition, hyperprolactinemia attenuate adiponectin expression in adipose tissue, which also decrease insulin sensitivity." (PMID 36993818, 2023). "Consequently, the metabolic effects of timed daily bromocriptine treatment observed in this study may in part derive from a reduction of plasma hyperprolactinemia and normalization of the daily rhythm of plasma prolactin level towards that of lean, insulin sensitive rats." (PMID 25937836, 2014). "Accordingly, treating hyperprolactinemia in patients without CKD with dopamine agonists results in weight loss, increased insulin sensitivity, and improved lipid profiles." (PMID 40650124, 2025). "Thus, activation of hypothalamic dopaminergic neurotransmission by dopamine agonists can reduce incidence and prevalence of MetS in patients with hyperprolactinaemia by controlling of PRL release and improving of insulin sensitivity." (PMID 39663784, 2024). "Mechanistically, pathological hyperprolactinemia has a negative effect on post-prandial insulin sensitivity." (PMID 36993818, 2023).
hyperprolactinemia (continued). "Hyperinsulinemic-euglycemic clamp studies demonstrated post-prandial hyperinsulinemia and a significant decrease in peripheral post-prandial insulin sensitivity in both hyperprolactinemia obese and non-obese subjects." (PMID 36993818, 2023). "We found that subjects with hyperprolactinemia had higher insulin levels and HOMA-IR indices than those without hyperprolactinemia." (PMID 34421613, 2021). "Compared with participants not diagnosed as having hyperprolactinemia, those with hyperprolactinemia were younger, were less likely to have a spouse or partner, and recorded higher ASEX scores, prevalence of sexual dysfunction, insulin levels, and HOMA-IR indexes." (PMID 34421613, 2021).
hypoadiponectinemia (32 papers, 2006 to 2025). "Adiponectin plays a critical role in insulin sensitivity and inflammation, and thus hypoadiponectinemia is thought to be linked with multiple metabolic risk factors." (PMID 32397260, 2020). "TLR9’s role in hypoadiponectinemia has implications for insulin sensitive tissues throughout the body." (PMID 33584545, 2020). "The link between hypoadiponectinemia and reduced insulin sensitivity is apparent as adiponectin levels show a decrease towards end of gestation in healthy women." (PMID 30123262, 2018). "However, there are few reports regarding affection of histological severity of NAFLD on insulin secretion, although hypoadiponectinemia caused by histological severity of NASH may predict impairment of insulin secretion in nondiabetic nonobese patients with NASH." (PMID 28878826, 2017). "EPA exerts an antidiabetic effect in InsrP1195L/+/HFD mice, an HFD-sensitive, insulin-resistant animal model, possibly through its action against hypoadiponectinemia." (PMID 27348201, 2016). "On the other hand, the decreased expression of these receptors is thought to be responsible for the hypoadiponectinemia, which leads to insulin insensitivity; thus, the adiponectin/insulin resistance relationship resembles what is called “vicious cycle”." (PMID 22649556, 2012). "Interestingly, a study has shown that MTF (or insulin) inhibits the development of hypoadiponectinemia and prevents the downregulation of APPL1 in mesenteric resistance arteries." (PMID 35409282, 2022). "In contrast, the levels of serum insulin and triglyceride further increased and the level of serum SHBG decreased in the puberty of PCOS offspring, and hypoadiponectinemia occurred much earlier than hyperandrogenemia." (PMID 33455575, 2021). "Accordingly, EPA might improve insulin signaling in adipocytes of InsrP1195L/+/HFD mice, which could ameliorate their hypoadiponectinemia." (PMID 27348201, 2016). "A previously published study, involving mainly Caucasian patients treated with antiretrovirals, found a correlation between low 25(OH)D and high insulin levels, but not lipoatrophy or hypoadiponectinemia." (PMID 24058636, 2013).
renal cell carcinoma (32 papers, 2002 to 2025). "Functional analysis of the miRNAs regulating the switch genes was associated with insulin signaling, signaling pathways regulating pluripotency of stem cells, and renal cell carcinoma." (PMID 35370543, 2022). "In contrast, pathways uniquely associated with F-asymAD switch genes are insulin secretion, progesterone-mediated oocyte maturation, axon guidance, renal cell carcinoma, and ErbB signaling pathway." (PMID 36389068, 2022). "Increased insulin sensitivity might be a mechanism by which alcohol intake reduces renal cell cancer risk." (PMID 17653076, 2007). "By means of GSEA, we identified five ADAMTS14-related signaling pathways, including MTOR, PPAR, INSULIN signaling pathway, renal cell carcinoma, and renin–angiotensin system." (PMID 35572505, 2022). "Patients in the low-risk group mainly involved in the ERBB signaling pathway, MAPK signaling pathway, MTOR signaling pathway, WNT signaling pathway, insulin signaling pathway, and renal cell carcinoma pathway, etc." (PMID 33976736, 2021). "Protein processing in the endoplasmic reticulum, insulin resistance, thyroid hormone signaling pathway, proteoglycan in cancer, renal cell carcinoma, adherent junction, and others were found." (PMID 33800744, 2021). "These genes were classified into different biological pathways, including signaling pathways of insulin, neurotrophin, estrogen, ErbB, and GnRH and pathways of chronic myeloid leukemia, ubiquitin mediated proteolysis, spliceosome, melanogenesis, and renal cell carcinoma." (PMID 37711168, 2023). "Similarly, unique pathways identified from F-asymAD switch genes were axon guidance, progesterone-mediated oocyte maturation, insulin secretion, renal cell carcinoma, and ErbB signaling." (PMID 36389068, 2022). "Insulin and IGFs have been reported to stimulate renal cell carcinoma cells growth and migration." (PMID 36199443, 2022). "According to the threshold of the |NES| >1.5 and nominal p-value < 0.05, we identified five signaling pathways that showed significantly different enrichment in the ADAMTS14 expression phenotype, including INSULIN, MTOR, PPAR, renal cell carcinoma, and renin–angiotensin system pathways." (PMID 35572505, 2022). "Also, both insulin and IGF-I might contribute to the growth and proliferation of renal cell cancer." (PMID 11986775, 2002).
tuberculosis (32 papers, 2005 to 2025). A chronic, recurrent infection caused by the bacterium Mycobacterium tuberculosis. "Loss of adipose tissue due to increased lipolysis during tuberculosis leads to release of free fatty acids which in turn disrupts insulin signaling pathway in skeletal muscles and can cause systemic insulin resistance." (PMID 37434784, 2023). "Thus, it seems that associations of low prior BMI, in most cases in the CICADA population in association with HIV or tuberculosis, with low plasma insulin could be due to prolonged undernutrition or other factors associated with poverty." (PMID 33740034, 2021). "Although several studies have shown the role of insulin in cellular metabolism and phagocytosis of M. tuberculosis, little is known about insulin resistance as a potential risk factor for active TB." (PMID 28245710, 2017). "Efforts have been made to develop such a standardized framework, which has already been applied to generic medicines on the WHO Essential Medicines List, insulin analogues, treatments for tuberculosis, and cancer medicines." (PMID 39495345, 2024). "Future plans include incorporating insulin and tuberculosis screening and treatment into CCMDD." (PMID 37408477, 2023). "Indeed, diabetic patients have been shown to be more susceptible to pulmonary infections such as tuberculosis, but the correlation between insulin signal and C. neoformans infection has not yet been investigated." (PMID 31329596, 2019). "Thus, it is tempting to propose that M. tuberculosis infection, which activates mTORC1 in an insulin-independent fashion (and this work), may contribute to insulin desensitization during tuberculosis." (PMID 30161232, 2018). "Select patients, like insulin-dependent or poorly controlled diabetics or patients with labile hypertension, tuberculosis, or peptic ulcer disease may not be able to tolerate oral steroid treatment." (PMID 29468101, 2017). "Mothers take children for vaccines and acute illnesses, but only a tuberculosis diagnosis results in chronic care involving long-term drug administration that can reasonably be expected to be available (such medications as insulin and oncology drugs are not available in the rural clinics)." (PMID 25330113, 2014).
Brain atrophy (31 papers, 2012 to 2025). Partial or complete wasting (loss) of brain tissue that was once present. "Improved insulin sensitivity over the trial was the parameter most strongly associated with brain atrophy attenuation (P < 0.05)." (PMID 35021194, 2022). "Therefore, ethanol-associated brain atrophy and degeneration may be mediated in part by the inhibition of insulin-Akt stimulation of ASPH and attendant CNS cellular senescence and apoptosis." (PMID 35625605, 2022). "A major goal of this study was to characterize the early- versus late-stage effects of heavy ethanol consumption on the insulin/IGF-1-Akt-mTOR pathway in relation to brain atrophy." (PMID 40149949, 2025). "Insulin therapy also shows significant benefits: subcutaneous insulin prevents brain atrophy, reduces hippocampal Aß42 and partially prevents tau hyperphosphorylation." (PMID 41146261, 2025). "Numerous studies have demonstrated that the administration of IGF-1 lessened brain atrophy, brain insulin resistance, apolipoprotein E-related neuropathology, and neurotransmitter secretion." (PMID 38473814, 2024). "Our results indicate that stress and insulin responses and cytokines associated with recruitment of inflammatory cells in MCI-AD are associated with its characteristic AD-like brain atrophy pattern and correlate with clinical changes or CSF biomarkers." (PMID 23408997, 2013). "This trial studies the effects of IN insulin on cognition and brain atrophy." (PMID 34948054, 2021). "Despite the lack of information regarding the basic underlying mechanisms involved in the development of T2D-mediated AD, some common features of the two conditions have been reported, such as brain atrophy, reduced cerebral glucose metabolism, and insulin resistance." (PMID 33728019, 2021). "We speculated that NNT and RFX5 may be involved in the secretion of insulin and the abnormity of these loci may be related to the whole brain atrophy, leading to the enlargements of ventricular system structures in AD." (PMID 31775305, 2019). "Higher insulin levels in the brain are correlated with lower rates of whole-brain atrophy in AD." (PMID 31775305, 2019). "On the other hand, regarding increased BMI, increased visceral fat deposition might affect brain atrophy and Aβ deposition through several potential mechanisms, including increased insulin resistance, lower levels of adipose-derived hormones, and a larger pattern of proatherogenic gene expression." (PMID 35936766, 2022). "This trial is studying the effects of insulin supplied intranasally on cognition and brain atrophy; it is not actually certain how insulin administered by this way affects tau protein." (PMID 31572186, 2019). "Furthermore, impaired brain insulin and IGF signaling induced in rats by intracerebral injection of streptozotocin results in brain atrophy and neurodegeneration." (PMID 30061810, 2018). "The localization of brain atrophy in T2DM to the ventral striatum, followed by the cerebellum, may reflect the fact that these two brain regions contain the densest concentrations of insulin-dependent GLUT-4 compared to non-insulin-dependent isoforms GLUT-1 and GLUT-3." (PMID 35608247, 2022). "While we did not detect any effects on cortical insulin or insulin-like growth factor 1 receptor m-RNA levels, LRGT significantly reduced brain atrophy in the db/db and APP/PS1xdb/db mice." (PMID 34975451, 2021).